APLN (apelin)
Diseases named in the same sentence as APLN in open-access papers (continued):
Sharing a sentence is not in itself a finding about the gene and the disease.
prostate carcinoma (continued). "Additionally, apelin blockade reduced metastatic tumor size in the lung, liver, and bone by 78.9%, 95.6%, and 96.1%, respectively, as determined by H&E staining, suggesting that inhibiting apelin suppresses prostate cancer metastasis." (PMID 40612675, 2025). "However, the effects of apelin in prostate cancer metastasis is undetermined." (PMID 36291151, 2022). "Thus, apelin facilitates prostate cancer disease by inhibiting TIMP2 expression." (PMID 36291151, 2022). "Importantly, apelin blockade inhibits prostate cancer metastasis in the orthotopic mouse model." (PMID 36291151, 2022). "Although, the effect of apelin upon prostate cancers metastasis is unknown." (PMID 36291151, 2022). "Importantly, apelin blockade inhibited prostate cancer metastasis in the orthotopic mouse model." (PMID 36291151, 2022). "Additionally, the 3′UTR of the APLN mRNA was complementary to miR-224, which might act as a tumor suppressor in human prostate cancer, suggesting that apelin is a direct target of miR-244." (PMID 29875677, 2018). "Apelin-induced STAT3 activation was blocked by treatment with ERK, p38, and JNK inhibitors, indicating that apelin enhances integrin-dependent prostate cancer migration via the MAPK and STAT3 pathways." (PMID 40612675, 2025). "Apelin promotes wound healing migration in both PC3 and DU145 prostate cancer cells in a concentration-dependent manner." (PMID 40612675, 2025). "In current study found that apelin increases c-Src phosphorylation, while the c-Src inhibitor or siRNA reversed apelin-regulated TIMP2 synthesis and the motility of prostate cancer cells." (PMID 36291151, 2022). "In this study, stimulation of prostate cancer cells with apelin abolished TIMP2 expression by a greater extent than TIMP1 or TIMP3, suggesting that TIMP2 is more important than other TIMPs in apelin-mediated motility of prostate cancer cells." (PMID 36291151, 2022). "Treating prostate cancer cells with PI3K and Akt inhibitors or transfecting them with PI3K and Akt siRNAs reversed apelin-mediated effects upon TIMP2 synthesis, cell motility and miR-106a-5p synthesis." (PMID 36291151, 2022). "Apelin suppresses TIMP2 production and subsequently facilitates the metastatic potential of human prostate cancer cells by increasing miR-106a-5p synthesis via the c-Src, PI3K and Akt signaling cascades." (PMID 36291151, 2022). "Cells were applied with the miR-106a-5p inhibitor reversed apelin-induced regulation of TIMP2 expression and prostate cancer cell motility." (PMID 36291151, 2022). "We now have a better understanding about how apelin-mediated miRNA and TIMP2 synthesis contributes to prostate cancer cell motility, which may help investigators design more effective treatment for metastatic disease." (PMID 36291151, 2022). "c-Src, PI3K and Akt inhibitors, as well as their respective siRNAs, inhibited apelin-facilitated promotion of miR-106a-5p synthesis, suggesting that apelin inhibits TIMP2 synthesis and facilitates prostate cancer migration by increasing miR-106a-5p production through the c-Src/PI3K/Akt pathway." (PMID 36291151, 2022). "Apelin facilitates TIMP2-dependent migration and invasion of prostate cancer cells." (PMID 36291151, 2022). "Additionally, apelin-induced inhibition of miR-8070 synthesis was reversed by blocking ERK, p38, and JNK expression, indicating that apelin regulates integrin production and cell motility in prostate cancer by reducing miR-8070 levels through the MAPK pathway." (PMID 40612675, 2025). "Our results also reveal that apelin enhances PI3K and Akt phosphorylation, which was antagonized by the c-Src inhibitor, suggesting that c-Src-dependent PI3K/Akt activation mediates apelin-controlled TIMP2 synthesis and the metastasis of human prostate cancer cells." (PMID 36291151, 2022). "However, apelin treatment did not affect the cell viability in prostate cancer cell lines." (PMID 40612675, 2025).
prostate carcinoma (continued). "Moreover, incubation with ERK, p38, and JNK inhibitors counteracted the apelin-induced effects on miR-8070 synthesis but not on WT luciferase activity, suggesting that apelin promotes integrin-dependent prostate cancer motility by suppressing miR-8070 via the MAPK pathway." (PMID 40612675, 2025).
type 1 diabetes (11 papers, 2012 to 2025). "In a type 1 diabetes mouse model, apelin-13 treatment reduced glomerular hypertrophy and mesangial matrix deposition, decreased albuminuria, and delayed renal inflammation." (PMID 41515992, 2025). "Case–control studies in children with type 1 diabetes have reported consistently higher apelin levels compared to healthy controls." (PMID 41515992, 2025). "In type 1 diabetes, apelin therapy (400 pmol/kg) for 10 weeks enhanced pancreatic islet mass, insulin content, and reduced endoplasmic reticulum stress in the pancreatic islets." (PMID 37424869, 2023). "In the streptozotocin-induced type 1 diabetes model, decreased insulin levels is accompanied by a decrease in apelin levels." (PMID 37424869, 2023). "Type 1 diabetes induced a down-regulation of apelin gene transcription in each depot, which was restored in eWAT and rWAT and up-regulated in scWAT compared to the control." (PMID 25170835, 2014). "In a small sample of children with type 1 diabetes apelin levels were reported to be increased compared to healthy controls." (PMID 23227256, 2012). "This important effect of apelin-13 in type 1 diabetes was mediated by inhibition of inositol requiring enzyme 1-α and JNK pathways, suggesting apelin effects on two important pathways of ER stress and cell death, respectively." (PMID 22655211, 2012). "Thus, it could be hypothesized that the increased plasma apelin observed in type 2 diabetic patients, is, as in type 1 diabetes, a compensatory mechanism devoted to directly decrease insulin resistance since apelin exerts different metabolic actions itself." (PMID 25914650, 2015). "In patients with type 1 diabetes we observed levels of apelin comparable to non-diabetic controls." (PMID 23227256, 2012).
dilated cardiomyopathy (10 papers, 2014 to 2025). Cardiomyopathy which is characterized by dilation and contractile dysfunction of the left and right ventricles. "Other overlapping downregulated pathways include chemical carcinogenesis—ROS, Rap1 signaling, fatty acid metabolism, apelin signaling, and salmonella infection, while overlapping upregulated pathways include dilated cardiomyopathy." (PMID 40293407, 2025). "In terms of beneficial effects, apelin improved cardiac function in mice with post-myocardial infarction heart failure dilated cardiomyopathy." (PMID 37942483, 2023). "In human cardiac tissues, APJ receptor density was significantly decreased in the left ventricle of patients with dilated cardiomyopathy, but apelin levels remained unchanged, suggesting that lowered receptor density may limit the positive inotropic influence of apelin." (PMID 41155377, 2025). "Furthermore, a KEGG pathway annotation analysis of differentially regulated genes associated with HFD identified a number of relevant pathways, most notably hypertrophic cardiomyopathy, pro-angiogenic apelin signaling, vascular smooth muscle contraction, and dilated cardiomyopathy (DCM)." (PMID 35896539, 2022). "At 41°C, meanwhile, the DEGs were enriched in the MAPK signaling pathway, the apelin signaling pathway, the PPAR signaling pathway, cardiac muscle contraction, hypertrophic cardiomyopathy, and dilated cardiomyopathy." (PMID 36213238, 2022).
osteoporosis (10 papers, 2018 to 2026). A condition of reduced bone mass, with decreased cortical thickness and a decrease in the number and size of the trabeculae of cancellous bone (but normal chemical composition), resulting in increased fracture incidence. "Moreover, FMT from exercised osteoporotic mice effectively activated apelin signaling pathway, alleviated systemic inflammation, and delayed the onset of osteoporosis in estrogen-deficient recipients." (PMID 39897551, 2025). "Notably, the level of apelin in plasma gradually decreases with age, and this decline is associated with age-related muscle loss and osteoporosis." (PMID 38249295, 2023). "One study found that the serum levels of Apelin-13 and 25-hydroxyvitamin D3 (25(OH)D3) are significantly lower in patients with osteoporosis than in healthy people, suggesting that Apelin-13 might be associated with bone metabolism." (PMID 38089606, 2023). "A study reported decreased expression of both apelin-13 and vitamin D3 in osteoporosis patients versus healthy controls." (PMID 36831180, 2023). "In contrast, a more recent study demonstrated that apelin was down-regulated in rats with ovariectomy-induced osteoporosis, and treatment with apelin-12 restored bone mass and microstructure." (PMID 36831180, 2023). "The level of Apelin-13 in osteoporosis group was significantly lower than that in osteopenia and normal groups (p<0.05), and the value in osteopenia group was significant lower than that in normal group (p<0.05)." (PMID 29643899, 2018). "The level of Apelin-13 in osteoporosis group was significantly lower than that in osteopenia and normal groups (p<0.05), and the value in osteopenia group was also significantly lower than that in normal group (p<0.05)." (PMID 29643899, 2018). "Taken together, the exercise-matched FMT might trigger the apelin pathway and reoriented differentiation path in MSCs from aged mice, thereby reversing the age-induced osteoporosis." (PMID 39897551, 2025). "Others play a certain role in cancer, osteoporosis, and energy regulation; the Apelin signaling pathway has a certain effect on the reproductive regulation of the hypothalamus, and this pathway is related to the treatment of cancer, glucose and lipid metabolism, and cardiovascular disease." (PMID 39794954, 2024). "Fortunately in the past few years, novel adipokines have been identified such as visfatin, LCN2, nesfatin-1, RBP-4, apelin, and vaspin that may have osteoprotective/osteoanabolic effects and thus could serve as potential therapeutic targets for osteoporosis and other metabolic bone diseases." (PMID 36831180, 2023). "A few observational studies in humans support the positive effect of apelin on BMD, though more studies are needed to determine its utility as a potential therapeutic target for osteoporosis." (PMID 36831180, 2023). "Lower levels of apelin-13 have been reported in patients with osteoporosis compared to those found in non-osteoporotic individuals." (PMID 38516409, 2024). "Furthermore, in vivo therapeutic potential of MSC transplantation against osteoporosis, myocardial injury, and hindlimb ischemia was strengthened by either apelin pretreatment or concomitant administration of MSC and apelin." (PMID 36750692, 2023). "Likewise, another study demonstrated significantly lower levels of apelin-13 in subjects compared to those without osteoporosis." (PMID 36831180, 2023).
polycystic ovary syndrome (10 papers, 2014 to 2023). A disorder that manifests as multiple cysts on the ovaries. "However, higher serum chemerin, apelin and vaspin levels have earlier been reported in women with polycystic ovary syndrome and hyperandrogenemia." (PMID 32580404, 2020).
pulmonary fibrosis (10 papers, 2019 to 2024). Chronic progressive interstitial lung disorder characterized by the replacement of the lung tissue by connective tissue, leading to progressive dyspnea, respiratory failure, or right heart failure. "Although apelin exerts effective preventing and alleviating effects against silica-induced pulmonary fibrosis, its underlying mechanism is unclear." (PMID 37705751, 2023). "We found that the serum level and pulmonary expression of apelin reduced dramatically in both silicosis patients and silica-induced fibrotic mice, which indicates that decreased apelin levels might be associated with pulmonary fibrosis in silicosis." (PMID 37705751, 2023). "In an LPS-induced pulmonary fibrosis model, the apelin-APJ axis was found to regulate fibrosis through TGF-β1-mediated endothelium-mesenchymal transformation (EndMT)." (PMID 37513116, 2023). "We first assessed the level of pulmonary fibrosis between silicosis and apelin-treated lungs using several tissue staining methods." (PMID 37705751, 2023). "Apelin can also directly alleviate lipopolysaccharide-induced pulmonary fibrosis in mice by promoting angiotensin-converting enzyme 2 50 or suppressing TGF-β1 signaling." (PMID 37705751, 2023). "Pulmonary fibrosis occurs in many lung pathologies and there is evidence that apelin can help to prevent this." (PMID 31492821, 2019). "Therefore, we next applied exogenous apelin to silicotic mouse models to explore its effects against silica-induced pulmonary fibrosis." (PMID 37705751, 2023). "Firstly, we investigated the preventive potential of apelin against pulmonary fibrosis." (PMID 37705751, 2023). "Thus, our study provides overwhelming evidence for the use of apelin in the prevention and treatment of silica-induced pulmonary fibrosis." (PMID 37705751, 2023). "Our findings suggest that apelin may be of great potential to treat silicosis and other pulmonary fibrosis." (PMID 37705751, 2023). "Therefore, we further determined whether apelin could be effective against silica-induced pulmonary fibrosis when treating mice later in the disease course (administrated from day 15 to 28 or 56 after modeling)." (PMID 37705751, 2023). "Furthermore, in vivo data demonstrated that pre-treatment from day 3 and post-treatment from day 15 with apelin could both alleviate silica-induced pulmonary fibrosis in mice." (PMID 37705751, 2023). "However, the roles of apelin in the pathological process and the effects on pulmonary fibrosis, including silicosis, and its underlying mechanisms have not been elucidated." (PMID 37705751, 2023). "This change may attenuate the inhibitory effect of apelin on TGF-β1 signaling and collagen production, resulting in the promotion of pulmonary fibrosis." (PMID 37705751, 2023). "In addition, we proposed that apelin inhibited TGF-β-SAMD2/3 pathway in fibroblasts, leading to the alleviation of silica-induced pulmonary fibrosis." (PMID 37705751, 2023). "Our study suggested that apelin could prevent and reverse silica-induced pulmonary fibrosis by inhibiting the fibroblast activation through TGF-β1 signaling pathway, thus providing a new potential therapeutic strategy for silicosis and other pulmonary fibrosis." (PMID 37705751, 2023). "However, the role of apelin in pulmonary fibrosis has not yet been revealed." (PMID 37705751, 2023).
Anxiety (9 papers, 2020 to 2025). Intense feelings of nervousness, tension, or panic often arise in response to interpersonal stresses. "In the current study, we showed that the SNPs associated with low apelin expression levels were also associated with an increased risk of depression or anxiety in patients with CHD." (PMID 32849850, 2020). "This contrasts with a previous study that reported a correlation between serum apelin levels and depression and anxiety scores." (PMID 39769424, 2024). "Specifically, XYS improves anxiety or depressive-like behavior by modulating gut microbiota and immune function, regulating the Apelin-APJ System in the hypothalamus, and the structure of related brain regions." (PMID 35432560, 2022). "The goal of this study was to investigate the association between APLN/APLNR gene polymorphisms and the risk of depression and anxiety in CHD patients." (PMID 32849850, 2020). "Apelin exhibited a double-edged sword effect in animal models of depression and an anxiolytic effect in animal models of anxiety." (PMID 32231577, 2020). "In this study, we investigated the associations of four promising polymorphisms in the APLN/APLNR pathway with the risks of depression and anxiety in patients with CHD." (PMID 32849850, 2020). "Chronic i.p. injection of apelin-13 (20 nmol/kg/d) alleviated anxiety-like behavior induced by chronic normobaric hypoxia in mice." (PMID 32231577, 2020). "This is the first pharmacogenomics study to examine the associations between polymorphisms located in genes of the APLN/APLNR pathway and the susceptibility to depression and anxiety in patients with CHD." (PMID 32849850, 2020). "We further investigated the influence of APLN/APLNR pathway polymorphisms on the risks of depression and anxiety in patients with CHD." (PMID 32849850, 2020). "Previous studies have demonstrated that XYS could reverse chronic stress-induced anxiety-like symptoms by regulating the apelin-APJ system in the hypothalamus and activity of the HPA axis." (PMID 32256358, 2020). "Therefore, the present study aimed to evaluate the association between APLN and APLNR gene polymorphisms and the risk of comorbid depression and anxiety in Chinese patients with CHD." (PMID 32849850, 2020). "The present study supports the hypothesis that APLN/APLNR polymorphisms contribute to the susceptibility to depression and anxiety in Chinese patients with CHD." (PMID 32849850, 2020). "Increased serum APLN levels may be an independent predictor of depression and anxiety development in patients having peritoneal dialysis." (PMID 33033451, 2020). "Furthermore, increased levels of serum apelin have been shown to be significant independent predictors of the development of depression and anxiety in patients on peritoneal dialysis." (PMID 32849850, 2020). "Our principal findings demonstrated that genetic polymorphisms in the APLN/APLNR pathway might result in a potential risk for depression and anxiety in patients with CHD." (PMID 32849850, 2020). "For example, in peritoneal dialysis patients with depression and anxiety, serum apelin levels were significantly higher than in those without depression and anxiety." (PMID 39769424, 2024). "Peritoneal dialysis patients with depression and anxiety had a significantly higher serum apelin than those without depression and anxiety." (PMID 32231577, 2020). "The Apelin (APLN)/apelin receptor (APLNR) signaling pathway is a newly identified regulator in various cardiovascular diseases, which is considered as a candidate pathway for the occurrence of coronary heart disease (CHD), depression, and anxiety." (PMID 32849850, 2020). "Thus, the APLN/APLNR signaling pathway is considered a candidate pathway for the occurrence of CHD, depression, and anxiety." (PMID 32849850, 2020). "For example, patients on peritoneal dialysis, who had depression and anxiety, had higher serum apelin levels than those without depression and anxiety." (PMID 32849850, 2020).